FNIP1 (folliculin interacting protein 1)
Diseases named in the same sentence as FNIP1 in open-access papers (continued):
Sharing a sentence is not in itself a finding about the gene and the disease.
mastitis (1 paper, 2025). Inflammation of breast tissue during lactation or postpartum due to an obstructed duct or infection. "Here, the study reported that K. pneumoniae impaired mitochondrial function and inhibited milk fat and protein synthesis through activation of FNIP1 signaling, which led to inflammation and caused mastitis." (PMID 41206543, 2025). "In this study, we established a model of the bovine mammary gland injury induced by K. pneumoniae to explore the role and associated mechanisms of FNIP1 in the mastitis." (PMID 41206543, 2025). "Thus, the studies were conducted to clarify the role of FNIP1-mediated mitochondrial function in mastitis caused by K. pneumoniae in vivo and in vitro." (PMID 41206543, 2025). "The milk synthesis was inhibited in the mastitis induced by K. pneumoniae, which depended on FNIP1-mediated mitochondrial dysfunction." (PMID 41206543, 2025). "Folliculin interacting protein 1 (FNIP1) is a major metabolic regulator of mitochondrial function with proinflammatory capabilities, but its role in K. pneumoniae-induced mastitis is yet to be elucidated." (PMID 41206543, 2025). "In conclusion, K. pneumoniae inhibited mitochondrial function by activating FNIP1, which reducing the synthesis of milk fat and protein, thereby in turn lowers milk quality and induced mastitis." (PMID 41206543, 2025). "However, whether FNIP1 participates in the regulation of milk fat and protein synthesis during the infection induced by K. pneumoniae and what role FNIP1 plays in mitochondrial function have not been researched yet in the mastitis." (PMID 41206543, 2025).
motor neuron disease (1 paper, 2024). "A previous study of splicing events controlled by TDP-43 in the context of the motor neuron disease ALS identified a downregulated exon in Fnip1 transcripts." (PMID 39337533, 2024). "Reducing HIPK2 activity improves phenotypes in mouse models of motor neuron disease ALS and IL6 levels, and the splicing of Fnip1 is altered in ALS conditions." (PMID 39337533, 2024).
oncocytoma (1 paper, 2025). "There could be defects or dysregulation at any part of the folliculin/FNIP1-mTOR-TFEB axis that prevented the biogenesis of lysosome, as seen with oncocytoma." (PMID 40806782, 2025).
peripheral artery disease (1 paper, 2023). "Remarkably, in the mouse hindlimb ischemia model of peripheral artery disease, loss of myofiber FNIP1 resulted in improved recovery of blood flow." (PMID 37932296, 2023). "Furthermore, in a mouse hindlimb ischemia model of peripheral artery disease, the loss of myofiber FNIP1 significantly improved the recovery of blood flow." (PMID 37932296, 2023). "Importantly, the deletion of myofiber FNIP1 improved the recovery of blood flow in the murine hindlimb ischemia model of peripheral artery disease." (PMID 37932296, 2023). "Given that functional revascularization is vital to improve blood flow recovery and limit the ischemic damage of tissue, targeted modulation of myofiber FNIP1 may represent a potential avenue for therapeutic intervention in peripheral arterial diseases and cardiovascular diseases." (PMID 37932296, 2023).
renal cell carcinoma (1 paper, 2018). "Our results collectively define roles for Fnip1 in regulating kidney development and function, and provide a model for how loss of Fnip1 contributes to PKD and perhaps renal cell carcinoma." (PMID 29897930, 2018).
rhabdomyoma (1 paper, 2019). A benign mesenchymal tumor arising from skeletal or cardiac muscle. "Though the function of tumour-suppressor protein folliculin (FLCN) is still being confirmed, the identification of the FLCN-interacting protein, FNIP1 has generated much interest and could explain the association with rhabdomyomas." (PMID 29744825, 2019).
tumor (17 papers, 2015 to 2025). "Several immune compartments, including B and myeloid lineages that are affected by FNIP1 deficiency, have been implicated in tumor predisposition in different IEIs." (PMID 40699689, 2025). "The dual inactivation of FNIP1/2 in mouse kidneys leads to polycystic kidney enlargement akin to FLCN deficiency, highlighting their roles as tumor suppressors, as mice with FNIP1 and/or FNIP2 knockouts exhibit tumors in multiple organs." (PMID 40143966, 2025). "Single-cell sequencing technologies have been employed to explore variations in FNIP1 expression across different tumor cells, elucidating FNIP1’s complex role in tumor heterogeneity and progression." (PMID 40143966, 2025). "The contribution of cochaperones prefoldin, HOP, Aha1, p23, FNIP1/2 and Tsc1 as well as the chaperonin TRiC to tumor suppressor stability is also discussed." (PMID 39352796, 2024). "This increased expression of FNIP1/2 provides one potential mechanism to explain the tumor selectivity of Hsp90 inhibitors." (PMID 35883484, 2022). "We further demonstrate that FNIP1 and Tsc1 are capable of compensating for each other in the chaperoning of mutated FLCN tumor suppressor." (PMID 29774133, 2018). "Reintroducing FNIP2-WT in FNIP1/FNIP2 depleted cells resulted in decreased tumor size and FNIP2-3A mutant presented further suppressive effects." (PMID 28039480, 2017). "Despite these general associations, tumor development has not been reported in patients with FNIP1 deficiency to date." (PMID 40699689, 2025). "As FNIP1/2 and Tsc1, respectively, have established roles as guardians of these tumor suppressors, it follows that there may be a role for molecular chaperones in mediating FLCN and Tsc2 stability." (PMID 35883484, 2022). "Additionally, FNIP1 and FNP2 act as tumor suppressors too, since FNIP1 and/or FNIP2 knockout mice exhibit tumors in multiple organs." (PMID 33981707, 2021). "Thus, functional studies have shown that FNIP1 and FNIP2 act as tumor suppressors since mice deficient in FNIP1 and FNIP2 tumors display tumors developing at the level of several organs." (PMID 32751108, 2020). "Considering the close relationship between the FNIPs and FLCN it is not surprising that they have also been suggested to act as tumor suppressors, as mice deficient in FNIP1 and/or FNIP2 exhibit tumors in several different organs." (PMID 32195250, 2020). "Notably, our upregulated genes also included FNIP1 and FNIP2, encoding folliculin-interacting proteins 1 and 2, emphasizing the potential importance of this pathway in NB tumor suppression." (PMID 32537432, 2020). "Despite the progress reviewed here, it remains difficult to disentangle the cellular roles of FNIP1/2 in the regulation of AMPK and TFE3 from that of FLCN tumor suppressive function." (PMID 35883484, 2022). "Here we show that the tumour suppressor FLCN is an Hsp90 client protein and its binding partners FNIP1/FNIP2 function as co-chaperones." (PMID 27353360, 2016). "Our data showed that both FNIP1 and FNIP2 were overexpressed in RCC tumours compared with adjacent normal tissues." (PMID 27353360, 2016). "Previous work has shown that FNIP1 and FNIP2 are critical components of the FLCN complex and are essential for its tumour suppressive function." (PMID 27353360, 2016). "Interestingly, loss of FEM1B led to decreased lactate production, perhaps as a byproduct of FNIP1-dependent stabilization of FLCN and its recently described tumor suppressive effect on lactate dehydrogenase A." (PMID 35883484, 2022). "FNIP1 and FNIP2 were also found to be critical for the tumor-suppressive function of FLCN in kidney tissue, suggesting that the appearance of tumors in BHD patients may be caused by the loss of essential FLCN-FNIP interactions." (PMID 32195250, 2020).
tumor (continued). "Further experiments utilizing a FLCN construct harboring the germline mutation of this patient suggest that there may be some ability of FNIP1 and Tsc1 to compensate for one another in the chaperoning of the FLCN and Tsc2 tumor suppressors." (PMID 29774133, 2018). "Administration of RIP‐12 inhibited the growth of IMR‐32 cell‐derived xenograft tumors, as evidenced by reduction in tumor volume, weight, and Ki‐67 proliferative activity, along with up‐regulation of NR1D1, RIOK3, FLCN, or FNIP1 as well as down‐regulation of LAMP1." (PMID 40899609, 2025). "As FNIP1/2 and Tsc1 scaffold the tumor suppressors FLCN and Tsc2 to Hsp90, it follows that these co-chaperones may participate in the chaperoning of additional Hsp90-dependent tumor suppressor clients." (PMID 35883484, 2022). "FLCN has been shown to bind FNIP1, FNIP2, the Rag GTPases A and C/D, GABARAP and plakophilin-4 (refs 11, 12, 13, 14, 15, 16, 17, 18), but the biological significance of each of these interactions with regards to the tumour suppressor function of FLCN is under investigation." (PMID 28656962, 2017). "Importantly, FNIP1 and FNIP2 were essential also for the tumor suppressive function of FLCN at the level of kidney tissue, thus supporting the view that the development of kidney tumors in BHD patients may be due to the loss of essential FLCN-FNIP interactions." (PMID 32751108, 2020). "In renal tumors, loss of FLCN-FNIP1/2 induces a non-classical interferon response, and FNIP1 and FNIP2 are crucial for FLCN’s tumor suppressor function." (PMID 37341987, 2023). "Notably, FNIP1/FNIP2 double knockdown promoted cell proliferation and migration, which were suppressed by reintroducing the non-degradable FNIP2 mutant, validating the critical tumor suppressor role of FNIP proteins." (PMID 28039480, 2017).
cancer (9 papers, 2016 to 2025). A tumor composed of atypical neoplastic, often pleomorphic cells that invade other tissues. "Dysfunctions in FNIP1 are associated with various types of cancer, including renal cell carcinoma." (PMID 40143966, 2025). "Future research should delve into the specific mechanisms of FNIP1 in various cancers and investigate how these findings can be translated into clinical applications, potentially leading to more targeted and effective treatments." (PMID 40143966, 2025). "FNIP1/2 were found overexpressed in cancer cell lines originating from several different tissues, and knockdown decreased sensitivity of these cancers to Hsp90 inhibition." (PMID 35883484, 2022). "In-Patient 1, variants in FNIP1, PPP1R15A, WDR19, and RUNX3 were present in ~100% of cancer cells across all samples." (PMID 34400647, 2021). "To link the high levels of FNIPs with sensitivity of cancer cells to Hsp90 inhibitors, we used siRNA to knock down FNIP1 and FNIP2 in LNCaP, T24, MCF7, H1299 and HT29 cells." (PMID 27353360, 2016). "Professor Leeanna found that FLCN, FNIP1, and FNIP2 are downregulated in various human cancers, particularly in poorly prognostic invasive basal-like breast cancer, as opposed to luminal, less aggressive subtypes." (PMID 40143966, 2025). "Additionally, FLCN and FNIP1, two regulators of energy homeostasis, were uniquely identified in HER2-enriched cancers." (PMID 40700427, 2025).
cardiovascular diseases (2 papers, 2023 to 2025). "Initially, FNIP1 is involved in regulating cellular energy metabolism and glucose homeostasis, which are linked to common metabolic disorders in cardiovascular diseases such as atrial fibrillation and arrhythmias." (PMID 40143966, 2025). "Studies indicate that metabolic disorders are a significant cause of cardiovascular diseases, and FNIP1 may act as a key regulator in these disorders, playing a crucial role in the pathogenesis of cardiovascular conditions." (PMID 40143966, 2025). "FNIP1 is clsely associated with the onset and progression of cardiovascular diseases." (PMID 40143966, 2025). "Moreover, studies have found that the expression levels of FNIP1 in patients with cardiovascular diseases are closely linked to treatment outcomes, potentially making FNIP1 an important marker for evaluating the effectiveness of cardiovascular disease treatments and guiding personalized therapy." (PMID 40143966, 2025). "Consequently, FNIP1 could serve as a biomarker for assessing cardiovascular disease risk and predicting disease progression." (PMID 40143966, 2025). "Research on FNIP1’s functions offers new insights and potential strategies for treating mitochondrial diseases, cardiovascular diseases, musculoskeletal disorders, disease prognosis assessment, and personalized medicine." (PMID 40143966, 2025). "Furthermore, FNIP1 is closely related to processes such as cardiomyocyte proliferation, apoptosis, and angiogenesis, which play key roles in the development of cardiovascular diseases." (PMID 40143966, 2025).
infection (2 papers, 2024 to 2025). The state of being infected such as from the introduction of a foreign agent such as serum, vaccine, antigenic substance or organism. "Indeed, mRNA and protein levels of FNIP1 increased significantly with the increase of infection time of K. pneumoniae in BMECs." (PMID 41206543, 2025). "In FNIP1/2-DKO cells where the FLCN-FNIP complex cannot form, TFEB is localized in the cell nucleus, regardless of infection status, as expected." (PMID 39572689, 2024).
metabolic disorders (2 papers, 2025). "Understanding the mechanistic basis of FNIP1 dysfunction in human tissues will be critical for delineating its contributions to immune and metabolic disorders and identifying targeted interventions." (PMID 40699689, 2025). "Additionally, research should also explore the role of FNIP1 in oncological diseases, such as its potential involvement in metabolic disorders, neurological diseases, and other possible pathological conditions." (PMID 40143966, 2025).
kidney diseases (1 paper, 2023). "Noteworthy candidates supported by kidney phenotypes in model organisms but not yet established as human kidney disease genes include EPB41L5 and FNIP1." (PMID 36890159, 2023).
mitochondrial disease (1 paper, 2025). "This provides a reference for future development of FNIP1-targeted drug therapies for mitochondrial diseases and improving patients prognosis with reduced stress, inflammatory response, skeletal muscle damage, et." (PMID 40143966, 2025). "Further research into the mechanisms of FNIP1’s role in the progression of mitochondrial diseases will aid in understanding the pathogenesis of these conditions and provide a theoretical basis for developing new treatment strategies." (PMID 40143966, 2025). "FNIP1 plays a crucial role in regulating cellular energy metabolism and mitochondrial function, making it a potential biomarker and therapeutic target in the study and treatment of mitochondrial diseases." (PMID 40143966, 2025). "The interaction between FNIP1 and FLCN critically regulates the mTOR pathway, affecting cellular responses to energy and nutrients, with aberrant activation of these pathways closely associated with the progression of mitochondrial diseases." (PMID 40143966, 2025). "The development of drugs targeting FNIP1, whether small molecule inhibitors or activators, may pave new therapeutic pathways, particularly for types of mitochondrial diseases where traditional treatments are ineffective." (PMID 40143966, 2025). "Consequently, therapeutic strategies targeting FNIP1 could represent a new approach to the treatment of mitochondrial diseases." (PMID 40143966, 2025).
FNIP1 also shares sentences with these, for which no sentence is quoted: B cell deficiency (2 papers); B-cell lymphopenia (2); prostate carcinoma (2); atrial fibrillation and flutter (1); atrial septal defect (1); Cirrhosis (1); colorectal cancer (1); diabetes (1); Duchenne muscular dystrophy (1); enteropathy (1); gastrointestinal infections (1); Insulin resistance (1); ischemic disease (1); limb ischemia (1); liver cysts (1); malignant mesothelioma (1); metabolic myopathy (1); musculoskeletal disorders (1); neutropenia (1); non-melanoma skin carcinoma (1); optic atrophy (1); Parkinson (1); Primary Immunodeficiency (1); sarcopenia (1); Wolff-Parkinson-White (WPW) syndrome (1).